ENSG00000265303 (novel protein)
Gene: Protein-coding gene on chromosome 17 (59,197,566 to 59,215,226, forward strand). Ensembl gene ENSG00000265303.
Genetic constraint (gnomAD): Loss-of-function variants: 4 observed, 6.29 expected, observed/expected ratio (o/e) 0.64, 90% interval 0.31 to 1.43. That is too few expected variants to judge how well the gene tolerates losing a copy. Missense variants: 47 observed, 57.7 expected, observed/expected ratio (o/e) 0.81, 90% interval 0.64 to 1.04. Synonymous variants: 17 observed, 21.77 expected, observed/expected ratio (o/e) 0.78, 90% interval 0.53 to 1.17.